FGFR2 (fibroblast growth factor receptor 2)
Diseases named in the same sentence as FGFR2 in open-access papers (continued):
Sharing a sentence is not in itself a finding about the gene and the disease.
myxoid liposarcoma (3 papers, 2015 to 2019). A liposarcoma characterized by the presence of round non-lipogenic primitive mesenchymal cells and small signet ring lipoblasts within a myxoid stoma with a branching vascular pattern. "The present study has revealed the receptor tyrosine kinase fibroblast growth factor receptor 2 (FGFR2) as a gene of interest being highly overexpressed in myxoid liposarcoma." (PMID 26036639, 2015). "FGFR2 expression was further analyzed in primary tumors and myxoid liposarcoma cell lines were treated with FGFR silencing siRNAs and tyrosine kinase inhibitors." (PMID 26036639, 2015). "In conclusion, our study revealed overexpression of FGFR2 as well as a functional role of FGFR signaling in myxoid liposarcoma and provides basis for the use of FGFR inhibitors as a novel targeted treatment approach for these tumors." (PMID 26036639, 2015). "FGFR2 protein expression was also present in the myxoid liposarcoma cell lines MLS 402 and MLS 1765." (PMID 26036639, 2015). "One of these genes was FGFR2, which was highly overexpressed in myxoid liposarcoma." (PMID 26036639, 2015). "In addition to FGFR2 also other members of the FGF/FGFR family showed an overexpression in the microarray analyses further reinforcing the potential role of FGFR signaling in myxoid liposarcomas." (PMID 26036639, 2015). "Our study demonstrates overexpression of FGFR2 and a functional role of FGFR signaling in myxoid liposarcoma." (PMID 26036639, 2015).
nasopharyngeal carcinoma (3 papers, 2024 to 2025). A carcinoma arising from the nasopharyngeal epithelium. "In nasopharyngeal carcinoma (NPC), cancer-associated fibroblast-derived fibroblast growth factor 5 (FGF5) activates fibroblast growth factor receptor 2 (FGFR2)–Nrf2 signaling, thereby dampening cisplatin-induced ferroptosis and promoting chemoresistance." (PMID 40867889, 2025). "For example, in nasopharyngeal carcinoma, CAFs secrete high levels of fibroblast growth factor 5 (FGF5), which binds to fibroblast growth factor receptor 2 (FGFR2) in tumor cells, hence inhibiting cisplatin-induced ferroptosis." (PMID 39614322, 2024).
orofacial cleft (3 papers, 2016 to 2022). A disorder of facial skeleton that is characterized by cleft lip and/or cleft palate that result in feeding, speech and hearing problems caused by failures during development. "Using peripheral blood, the role of FGFR1 and FGFR2 gene polymorphisms in orofacial cleft development has been researched, furthering the knowledge of orofacial cleft formation." (PMID 35455561, 2022). "Multiple studies have detected FGFR1 and FGFR2 expression in orofacial cleft tissue, therefore indicating a possible role in orofacial cleft morphopathogenesis." (PMID 35455561, 2022). "Even though the dysregulated function of FGFR1, FGFR2 and FOXO1 has been examined in non-syndromic orofacial clefts, there has been limited research regarding the comparison of these factors in one individual’s two separate locations—cleft-affected lip tissue and cleft-affected palatine tissue." (PMID 35455561, 2022). "Additionally, combining different methods to evaluate FGFR2 isoforms and FGFs could greatly impact the understanding of the roles of FGFR1, FGFR2 and FOXO1 in orofacial cleft development." (PMID 35455561, 2022). "Numerous intercorrelations between FGFR1, FGFR2 and FOXO1 do not exclude their role in the possible complex morphopathogenesis in each individual affected by orofacial clefts." (PMID 35455561, 2022).
renal aplasia (3 papers, 2010 to 2024). "We found that FGF10, presumably signaling via FGFR2, is an essential component of this alternative signaling, as removing either one or two Fgf10 alleles in a Gdnf−/−;Spry1−/− background caused failure of UB emergence, leading to renal agenesis." (PMID 20084103, 2010). "Taken together with the increased incidence of renal aplasia in Esrp1‐null mice, these findings suggest that Esrp1 is critical for Fgfr2 splicing in the ureteric epithelium to maintain ureteric epithelial architecture." (PMID 27404344, 2016). "Loss of Gdnf causes renal agenesis because in the presence of SPRY1 the level of FGF10 signaling via FGFR2 is not sufficient to produce the necessary responses, such as an appropriate level of Etv4 and Etv5 expression." (PMID 20084103, 2010). "When Spry1 is absent there is no brake on signaling via FGFR2, and GDNF can be removed without causing renal agenesis, due (at least in part) to the effects of FGF10, and to the restoration of Etv4/Etv5 expression; however, UB branching pattern is abnormal." (PMID 20084103, 2010).
renal carcinoma (3 papers, 2020 to 2024). A carcinoma arising from the epithelium of the renal parenchyma or the renal pelvis. "In renal cancer, FGF2 enhances cell proliferation by triggering the FGFR2 signalling pathway." (PMID 39091947, 2024).
tubular adenocarcinoma (3 papers, 2018 to 2023). An infiltrating adenocarcinoma in which the malignant cells form tubular structures. "Samples with high FGFR2 gene amplification were both of intestinal subtype (papillary or tubular adenocarcinoma) and diffuse type (poorly differentiated adenocarcinoma and signet-ring cell carcinoma)." (PMID 28852882, 2018). "Indeed, a tubular adenocarcinoma showed homogeneous FGFR2 amplification in the primary tumor while the corresponding lymph node metastasis showed no FGFR2 amplification." (PMID 36416959, 2023). "On the other hand, for papillary adenocarcinoma and moderately differentiated tubular adenocarcinoma, the proportions of HER2-positive patients were numerically higher than those for FGFR2-positive patients." (PMID 35585358, 2022).
uterine corpus endometrial carcinoma (3 papers, 2021 to 2023). A endometrial carcinoma (disease) that involves the body of uterus. "An FGFR2::ATE1 fusion was previously detected in one case of uterine corpus endometrial carcinoma in the TCGA dataset but with other exons fused." (PMID 36635225, 2023).
Anxiety (2 papers, 2022 to 2023). Intense feelings of nervousness, tension, or panic often arise in response to interpersonal stresses. "In contrast, FGFR2 loss in astrocytes starting at 8 weeks of age resulted only in reduced anxiety-like behavior." (PMID 36906620, 2023). "When FGFR2 was eliminated in embryonic pluripotent precursors or in early postnatal astroglia, mice were hyperactive, and had small changes in working memory, sociability, and anxiety-like behavior." (PMID 36906620, 2023). "Differences of FGFR2 iKO mice from wild type littermates were found only for anxiety-like behavior." (PMID 36906620, 2023). "Compared to their control littermates, FGFR2 cKO mice were more active in an open field, also spending more time in the center of the open field (p = 0.04)), a phenotype suggesting reduced anxiety-like behavior." (PMID 36906620, 2023). "For example, greater locomotor hyperactivity in the FGFR2 cKO mice compared to FGFR2 nKO and FGFR2 iKO may interact with their anxiety-like behavior regulation in complex ways." (PMID 36906620, 2023).
attention deficit-hyperactivity disorder (2 papers, 2023). A disorder characterized by a marked pattern of inattention and/or hyperactivity-impulsivity that is inconsistent with developmental level and clearly interferes with functioning in at least two settings (e.g. at home and at school). "Herein, we describe a 12-year-old Sicilian male patient with severe ASD, associated with Attention Deficit/Hyperactivity Disorder (ADHD), carrying a de novo variant in the fibroblast growth factor receptor 2 (FGFR2) gene." (PMID 37733178, 2023). "We conclude that altered astroglial cell function dependent on FGFR2 in the early postnatal period may result in impaired synaptic development and behavioral regulation, modeling childhood behavioral deficits like attention deficit hyperactivity disorder (ADHD)." (PMID 36906620, 2023).
bone mineralization disorder (2 papers, 2023 to 2025). "Clarifying the mechanism leading to FGFR2-related bone mineralization disorders and understanding its role in bone development and growth could also provide new insights to address new therapeutic approaches." (PMID 40362441, 2025).
cardiomyopathy (2 papers, 2021 to 2025). A disease of the heart muscle or myocardium proper. "Although no studies have specifically investigated the relationship between FGFR2 and TLR4, research has demonstrated that high glucose -induced activation of FGFR1 is mediated by TLR4 and c-Src in the context of cardiomyopathy." (PMID 40791737, 2025).
cervical squamous cell carcinoma (2 papers, 2019 to 2021). A squamous cell carcinoma arising from the cervical epithelium. "We found that decreased FGFR2 expression was associated with short patient OS in cervical squamous cell carcinoma and endocervical adenocarcinoma (CESC), EAC, HNSC, KIRC, LUAD, and LUSC, while increased FGFR2 expression was associated with short patient OS in KIRP." (PMID 33968743, 2021).
clear cell renal cell carcinoma (2 papers, 2016 to 2019). "E.g. the study of RNA sequencing data of clear cell renal cell carcinomas identified for FGFR2 transcripts a switch from IIIb to IIIc variant as associated with worse clinical features like higher grade and shorter survival." (PMID 27650542, 2016). "For example, in normal kidney FGFR2-IIIb is overexpressed in detriment of FGFR2-IIIc, while in clear cell renal cell carcinoma (ccRCC), FGFR2-IIIc becomes overexpressed in detriment of FGFR2-IIIb." (PMID 31881796, 2019).
cleft lip (2 papers, 2009 to 2015). Congenital defect in the upper lip where the maxillary prominence fails to merge with the merged medial nasal prominences. "However, it must also be emphasized that Esrp ablation also induces global changes in AS that surely contribute to the phenotypes we observe, including those, such as cleft lip, that were not identified in Fgfr2-IIIb KO mice." (PMID 26371508, 2015).
cutaneous squamous cell carcinoma (2 papers, 2024 to 2025). "The intent of this study was to evaluate the expression patterns of the NOTCH1 and FGFR2 genes and to explore potential correlations between them across successive histological stages of cutaneous squamous cell carcinoma." (PMID 39063983, 2024). "While our study provides significant insights into the expression patterns of NOTCH1 and FGFR2 in cutaneous squamous cell carcinoma (cSCC), there are several limitations to consider." (PMID 39063983, 2024). "In our study, we observed distinct expression patterns of NOTCH1 and FGFR2 across different histological stages of cutaneous squamous cell carcinoma (cSCC)." (PMID 39063983, 2024). "For example, there is evidence that loss of the tumor-suppressing lipid phosphatase PTEN and, thereby, induced autocrine FGF10/FGFR2 signaling may support the development of cutaneous squamous cell carcinoma (SCC)." (PMID 40724880, 2025).
dwarfism (2 papers, 2015 to 2022). "Mutation of the Fgfr2 gene is related to human dwarfism, and this gene was highly conserved during the evolution of different species." (PMID 35525962, 2022). "FGFR germline mutations (activating) can cause skeletal disorders, primarily dwarfism (generally mutations in FGFR3) and craniofacial malformation syndromes (usually mutations in FGFR1 and FGFR2)." (PMID 26224133, 2015). "FGFR germline mutations (activating) can cause skeletal disorders, primarily dwarfism (generally mutations in FGFR3), and craniofacial malformation syndromes (usually mutations in FGFR1 and FGFR2); intriguingly, some of these activating FGFR mutations are also seen in human cancers." (PMID 26224133, 2015).
endometrioid carcinoma (2 papers, 2022 to 2023). "FGFR2 in-frame deletion occurred in patients with ICC at the highest frequency (0.62%, 7/1122) compared with others, followed by lung squamous carcinoma (0.53%, 5/945) and endometrioid carcinoma (0.53%, 1/188)." (PMID 37964396, 2023).
fibrosis (2 papers, 2010 to 2023). the formation of excess fibrous connective tissue in an organ or tissue in a reparative or reactive process. "In the CCl4-induced mouse fibrosis model, the expression of FGFR2 was positively correlated with the expression of Actin Alpha 2 (ACTA2), an indicator of fibrosis, as the number of days of induction increased." (PMID 37111305, 2023). "Some of the most significantly activated canonical pathways included hepatic fibrosis/hepatic stellate cell activation (CD14, COL1A1, FGFR2, IGFBP3, MMP2, and TGFBR1), and p38 MAPK signaling pathways (CREB1, PLA2G2A, TGFBR1)." (PMID 20540791, 2010).
gastrointestinal stromal tumor (2 papers, 2025). "Constitutive FGFR2 signalling in gastrointestinal stromal tumours is triggered almost exclusively by two rare events: gene fusions that maintain the kinase domain but remove the extracellular region, and receptor amplifications that raise the density of the full length protein." (PMID 41150770, 2025).
Hydroureter (2 papers, 2011 to 2024). The distention of the ureter with urine. "Notably, mutations of FGFR2 in humans cause hydroureter and solitary kidney." (PMID 21637383, 2011). "Conditional inactivation of FGFR2 in the mesenchyme results in supernumerary UBs, duplex ureters, hydroureter, and renal agenesis." (PMID 21637383, 2011). "Conditional KO of Fgfr2 in metanephric mesenchyme cells leads to CAKUT in mice including hypo-/dysplastic kidneys and hydroureters." (PMID 38154558, 2024).
inflammatory skin disease (2 papers, 2020 to 2024). Inflammatory skin disorders covers a broad category that includes many conditions ranging in severity, from mild itching to grave medical health complications These disorders are common in people of all ages and races. "The downregulation of FGFR2 expression by pro-inflammatory stimuli pointed to a potential role of this receptor in the pathogenesis of inflammatory skin disease." (PMID 39340759, 2024). "However, the defect in the epidermal barrier and the resulting inflammatory skin disease that develops in mice lacking FGFR1 and FGFR2 in keratinocytes were further aggravated upon additional loss of FGFR3." (PMID 31830366, 2020).
influenza infection (2 papers, 2021 to 2025). "From MAGMAv1.07b, we identified three significant genes with a primary role in influenza infection: FGFR2, KPNB1 and NUP153." (PMID 33924631, 2021). "Our analysis coincides with previous findings linking the induced inactivation of FGFR2 with increased mortality and influenza-induced lung injury." (PMID 33924631, 2021).
intestinal tumor (2 papers, 2022 to 2023). "In contrast, in our cohort, we found a significant correlation between FGFR2 expression and the intestinal tumor type (p<0.001)." (PMID 35167603, 2022). "Our cohort even showed a slightly, although not significantly, higher percentage of FGFR2-amplified tumors within the group with diffuse histology compared with the ratio in intestinal tumors." (PMID 36416959, 2023).
invasive lobular carcinomas (2 papers, 2022 to 2024). "By contrast, the majority of Fgfr2ΔE18 glands contained FGFR2-positive high-grade adenocarcinomas or E-cadherin-negative invasive lobular carcinomas or sarcomatoid tumours." (PMID 35948633, 2022).
keloid (2 papers, 2016 to 2023). An irregularly shaped, elevated mark on the skin caused by deposits of excessive amounts of collagen during wound healing. "Previous studies have shown that the epithelial-mesenchymal transition in keloids is accompanied by abnormal alternative splicing of FGFR2 IIIb/IIIc." (PMID 36777722, 2023). "Moreover, AS of the FGFR2 gene switched the predominantly expressed isoform from FGFR2-IIIb to -IIIc, concomitant with the decreased expression of ΔNp63 and TAp63, which changes might partially account for abnormal epidermis and appendages in keloids." (PMID 36777722, 2023). "In the current study, the FGFR2 splicing regulator PTB, whose overexpression plays a pivotal role in tumour proliferation, invasion and metastasis, is demonstrated for the first time to be overexpressed in keloid tissues and fibroblasts." (PMID 27897224, 2016).
laryngeal squamous cell carcinoma (2 papers, 2019 to 2025). A squamous cell carcinoma that arises from the larynx. "While the precise mechanism by which Fgfr2 deficiency affects Fgfr1 and Fgfr4 mRNA expression remains unclear, a positive correlation between FGFR1 and FGFR2 expression has been documented in human laryngeal squamous cell carcinoma tissues." (PMID 41151533, 2025).
leukoplakia (2 papers, 2015 to 2024). A white patch or plaque on a mucous membrane that cannot be characterized clinically or pathologically as any other disease. "The present study was undertaken to analyze expression of FGF-2 and its receptors FGFR-2 and FGFR-3 in 72 PMOLs, 108 OSCC and 52 healthy controls, and their role in risk assessment for malignant transformation of Leukoplakia (LKP) and Oral submucous fibrosis (OSMF) to OSCC." (PMID 26465941, 2015).
liposarcoma (2 papers, 2015 to 2021). A usually painless malignant tumor that arises from adipose tissue. "Among the other liposarcoma subtypes, overexpression of FGFR2 has been reported in myxoid liposarcoma both in primary tumor samples and cell lines." (PMID 34204560, 2021). "FGFR2 expression in primary myxoid liposarcomas was also shown on protein level by immunohistochemistry and western blot analysis." (PMID 26036639, 2015). "In FGFR2-overexpressing myxoid liposarcoma cell lines, the FGFR TKIs PD173074, dovitinib and infigratinib, reduced cell proliferation and migration, and this effect was further increased by their combination with the standard chemotherapeutic agent trabectedin." (PMID 34204560, 2021).
medulloblastoma (2 papers, 2025). A malignant, invasive embryonal neoplasm arising from the cerebellum. "Germline mutations in FGFR2 have been described in medulloblastoma." (PMID 39851951, 2025).
metastatic cancer (2 papers, 2019 to 2025). A carcinoma which has spread from the original site of growth to another anatomic site. "The ReFocus trial (NCT04526106), a phase 1/2 open label global study, is currently evaluating the safety and efficacy of RLY-4008 in patients with advanced unresectable and/or metastatic cancers harbouring an FGFR2 alteration." (PMID 41351070, 2025). "Disease assessment after cycles 3 (November) and 6 (January) showed robust partial response by RECIST criteria, consistent with this novel FGFR2 fusion being a driver of his metastatic cancer." (PMID 31371345, 2019).
metastatic melanoma (2 papers, 2022 to 2023). A melanoma that has spread from its primary site to another anatomic site. "We demonstrate strong enrichment of ecDNA molecules containing EGFR, FGFR2 and MYC from human cancer cells and NRAS ecDNA from human metastatic melanoma with acquired therapeutic resistance." (PMID 36253572, 2022).
osteoglophonic dysplasia (2 papers, 2015 to 2019). A rare skeletal disorder characterized by dwarfism, severe craniofacial abnormalities and multiple unerupted teeth. "Cranial malformations arise in a range of diseases that involve activation of FGF23 receptors, including osteoglophonic dysplasia (OGD) (FGFR1,), Crouzon and Apert syndromes (FGFR2,) and achondroplasia (FGFR3,)." (PMID 30808384, 2019).
ovarian neoplasm (2 papers, 2023 to 2024). A benign, borderline, or malignant neoplasm involving the ovary. "Recent high-throughput mRNA sequencing studies and the ovarian neoplasm case spanned 26 samples with FGFR2 fusions, 21 of which had FGFR2 as the 5′ partner." (PMID 39759134, 2024). "To date, there is only one other case report of FGFR2 fusion-positive ovarian neoplasm." (PMID 39759134, 2024).